HSF1 (heat shock transcription factor 1)
Diseases named in the same sentence as HSF1 in open-access papers (continued):
Sharing a sentence is not in itself a finding about the gene and the disease.
gallbladder cancer (3 papers, 2021 to 2022). "Our data indicate the complicated process of the TSP-4/ integrin α2/HSF1/TGF-β cascades-mediated the reciprocal interaction in GBC cells and CAFs, providing a promising therapeutic target for gallbladder cancer patients." (PMID 33407730, 2021). "AKT-regulated phosphorylation of HSF1 at S326 promoted proliferation, epithelial-mesenchymal transition (EMT), and cancer stem-like traits in gallbladder cancer." (PMID 34239690, 2021). "Taken together, our data indicate the complex TSP-4/integrin α2/HSF1/TGF-β cascade mediates reciprocal interactions between GBC cells and CAFs, providing a promising therapeutic target for gallbladder cancer patients." (PMID 33407730, 2021). "Our data indicate that a complex TSP-4/integrin α2/HSF1/TGF-β cascade mediates reciprocal interactions between GBC cells and CAFs, providing a promising therapeutic target for gallbladder cancer patients." (PMID 33407730, 2021). "Collectively, these results led us to propose a model whereby CAFs-derived TSP-4 interacts with its receptor integrin α2 to activate the PI3K-Akt pathway, which results in HSF-1 activation that mediates the EMT and cancer stemness of gallbladder cancer." (PMID 33407730, 2021). "CAF-derived TSP-4 was shown to interact with the transmembrane receptor integrin α2 on GBC cells, which then activated Akt-mediated HSF1 activation to promote GSC cell proliferation and induce the EMT and cancer stem-like traits of gallbladder cancer." (PMID 33407730, 2021). "Thus, we further explored whether the downstream transcription factor HSF1 participates in the TSP-4/integrin α2 axis-induced EMT and cancer stem-like traits in gallbladder cancer." (PMID 33407730, 2021).
gastric adenocarcinoma (3 papers, 2017 to 2020). "We have also demonstrated that reduction in levels of Sp1 using mithramycin are associated with a reduction in HSP70 and HSF1, indicating that Sp1 lies upstream of these pro-survival factors in gastric adenocarcinoma cells." (PMID 28192510, 2017). "In light of these findings, the higher HSF1 levels of 23132/87 cells could have a protective role in the survival of these primary gastric adenocarcinoma cells under stress challenges." (PMID 32751694, 2020). "In particular, HSF1 knockdown reduced the proliferation, migration and invasiveness capabilities of AGS and MKN28 gastric adenocarcinoma cell lines." (PMID 32751694, 2020).
Hyperglycaemia (3 papers, 2017 to 2025). "HSP90 inhibitors reversed hyperglycaemia in diabetic db/db mice and improved insulin sensitivity in insulin-resistant obese mice, further supporting the concept that the HSF1 pathway is a potentially viable anti-diabetic target." (PMID 41488136, 2025). "Hepatic FAM3C overexpression activated HSF1-CaM-Akt pathway to repress gluconeogenic gene expression and ameliorate hyperglycemia of type 1 diabetic mice." (PMID 29285313, 2017). "In the current study, we demonstrated that hepatic FAM3C or HSF1 overexpression repressed gluconeogenic gene expression and attenuated hyperglycemia of type 1 diabetic mice." (PMID 29285313, 2017). "Overall, the changes in hepatic Akt phosphorylation and gluconeogenic gene expression were consistent with the amelioration of hyperglycemia after FAM3C or HSF1 overexpression." (PMID 29285313, 2017). "In the current study, we provided new evidences that FAM3C activated HSF1-CaM-Akt pathway to repress hepatic gluconeogenic gene expression and attenuate hyperglycemia of type 1 diabetic mice." (PMID 29285313, 2017). "In conclusion, FAM3C is a new hepatokine that activates HSF1-CaM-Akt pathway to ameliorate hyperglycemia of type 1 diabetic mice by suppressing hepatic gluconeogenesis in an insulin-independent manner." (PMID 29285313, 2017). "Given the important roles of HSF1 in regulating hepatic glucose and lipid metabolism by modulating Akt activity and molecular chaperone expressions, the side effects such as hyperglycaemia should be taken into consideration when HSF1 inhibitor is potentially used to treat cancers." (PMID 30887707, 2019). "Moreover, hepatic HSF1 overexpression also activated CaM-Akt pathway to repress gluconeogenic gene expression and improve hyperglycemia of type 1 diabetic mice." (PMID 29285313, 2017). "One is that although FAM3C activates HSF1-CaM pathway to activate Akt independent of insulin in cultured hepatocytes, whether it can suppress hepatic gluconeogenesis to improve hyperglycemia of type 1 diabetic mice remains unknown." (PMID 29285313, 2017).
Hypertension (3 papers, 2017 to 2023). The presence of chronic increased pressure in the systemic arterial system. "We propose that targeting of the HSF1 may develop novel promising strategies for the treatment of cardiac fibrosis and dysfunction in patients with disease such as hypertension, aortic valvular stenosis, and aortic constriction." (PMID 28091697, 2017). "Therefore, HSF1 upregulation may provide a new therapeutic strategy for the treatment of cardiac fibrosis induced by diseases such as hypertension, aortic valvular stenosis, and aortic constriction." (PMID 28091697, 2017).
sarcoma (3 papers, 2011 to 2022). A usually aggressive malignant neoplasm of the soft tissue or bone. "For example, HSPs suppress HSF1 activation, but Lee and his colleagues reported that HSP25 (HSP27) and HSP70 induce HSF1 activation in some sarcoma cells." (PMID 36430241, 2022).
sarcopenia (3 papers, 2014 to 2025). Progressive decline in muscle mass due to aging which results in decreased functional capacity of muscles. "Heat shock factor 1 (HSF1) is a transcription factor that orchestrates cellular responses to various stresses, while its role in sarcopenia remains unknown." (PMID 41400028, 2025). "However, functional coupling between heat shock proteins and SERCA activity has been described before and can potentially explain CDN1163-mediated restoration of SERCA activity as an activator of HSF1 in sarcopenia." (PMID 33375170, 2020). "We do not know the exact mechanism(s) by which CDN1163 treatment resulted in activation of HSF1 and suppression of p38 MAPK in sarcopenia." (PMID 33375170, 2020). "Thus, HSF1 regulates skeletal muscle functions and systemic energy homeostasis via the SIRT3-PGC1α axis, representing a potential therapeutic target for sarcopenia and metabolic disorders." (PMID 41400028, 2025).
Stroke (3 papers, 2019 to 2024). Sudden impairment of blood flow to a part of the brain due to occlusion or rupture of an artery to the brain. "Some immediate effects on lesion size 24 hours after stroke onset were observed in TTR deficient mice heterozygous for heat shock transcription factor 1 (HSF1)." (PMID 31479465, 2019). "Additionally, to further emphasize C19orf53’s potential impact on the risk of stroke, there exists a significant relationship between C19orf53 and Heat Shock Factor 1 (HSF1) discovered by the authors." (PMID 39337941, 2024). "The difference in lesion size and outcome between TTR deficient mouse strains might be explained by reduced or suppressed levels of HSF1 resulting in a compromised heat shock response during the first hours after stroke onset." (PMID 31479465, 2019). "Key proteins involved in mitochondrial stress, such as ATF5, ATF4, HSF1, FGF21, and GDF15, hold promise as potential targets for modulating neuroinflammation during stroke." (PMID 38321473, 2024).
synucleinopathy (3 papers, 2016 to 2017). A neurodegenerative disease that is characterized by the abnormal accumulation of aggregates of alpha-synuclein protein in neurons, nerve fibers or glial cells. "We recently identified aberrant HSF1 degradation via ubiquitin proteasome system as an important mechanism underlying synucleinopathy." (PMID 28678786, 2017). "Enhanced degradation of HSF1 by the proteasome has also been implicated in a mouse model and human post-mortem tissues of α-synucleinopathies, whereby elevated levels of the ubiquitin ligase, NEDD4, ubiquitinates HSF1 for degradation." (PMID 28923065, 2017). "Together with the finding that preserving HSF1 can alleviate α-synuclein toxicity, this study strongly suggests that aberrant HSF1 degradation is a key neurodegenerative mechanism underlying α-synucleinopathy." (PMID 26503960, 2016). "Indeed, two recent findings in an α-synucleinopathy and HD suggest a possible generic underlying pathology in NDs, whereby HSF1 is targeted for degradation by the proteasome through elevated expression or activity of ubiquitinases." (PMID 28923065, 2017). "Here we have provided compelling and novel in vitro and in vivo evidence that proteotoxic stresses, as exemplified by α-synucleinopathy, induce rapid and sustained HSF1 protein degradation mediated by the E3 ligase NEDD4 through UPS." (PMID 26503960, 2016). "Since reciprocal expression levels of NEDD4 and HSF1 were found in mouse and human tissue of α-synucleinopathy, we then sought in vivo evidence of α-syn-induced HSF1 degradation." (PMID 26503960, 2016). "HSF1 dysregulation via α-synuclein was confirmed by in vivo assessment of mouse and in situ studies of human specimens with α-synucleinopathy." (PMID 26503960, 2016).
T-cell acute lymphoblastic leukemia (3 papers, 2020 to 2023). Acute lymphoblastic leukemia of T-cell origin. "NOTCH binding to the HSF1 promoter was demonstrated in samples from patients with acute T-cell lymphoblastic leukemia, resulting in increased expression of HSF1 and its downstream effectors with subsequent activation of the cellular stress response machinery." (PMID 37894333, 2023).
type 2 diabetes mellitus (3 papers, 2017 to 2025). A type of diabetes mellitus that is characterized by insulin resistance or desensitization and increased blood glucose levels. "Because the observed associations were relatively weak, more research is needed to assess the relationship between HSF1 gene polymorphisms and susceptibility to type 2 diabetes in other populations around the world." (PMID 36431071, 2022). "Further research is warranted to substantiate the molecular mechanisms by which HSF1 gene polymorphisms are linked to the pathogenesis of type 2 diabetes." (PMID 36431071, 2022). "In conclusion, the present pilot study found, for the first time, that genetic variations of heat shock transcription factor 1 contribute to type 2 diabetes susceptibility in females with body mass index ≥ 25 kg/m2." (PMID 36431071, 2022). "Two haplotypes, such as rs7838717T-rs4279640T-rs3757971C and rs7838717T-rs4279640T-rs3757971T of HSF1, showed associations with increased and decreased risk of type 2 diabetes in overweight or obese females, respectively." (PMID 36431071, 2022). "The present study showed, for the first time, that genetic variation of HSF1 is associated with the risk of type 2 diabetes, supporting a role for impaired protein folding in disease pathogenesis." (PMID 36431071, 2022). "The aim of this pilot study was to investigate whether polymorphisms in the gene encoding heat shock factor 1 (HSF1), a transcriptional activator of molecular chaperones, play a role in the development of type 2 diabetes (T2D)." (PMID 36431071, 2022). "Therefore, the aim of this pilot study is to investigate whether single nucleotide polymorphisms (SNP) of the HSF1 gene are associated with the risk of type 2 diabetes." (PMID 36431071, 2022). "However, experimental studies are required to reproduce these molecular consequences of HSF1 deficiency and to draw definitive conclusions about the causal relationship between the HSF1 gene, molecular chaperones HSP90B1, HSPA5, and FKBP4, and impaired proinsulin folding in type 2 diabetes." (PMID 36431071, 2022). "Despite the fact that HSF1 activates almost all chaperones and regulates UPR, the genetic variability of this chaperone has never been considered as a potential factor that may contribute to the development of type 2 diabetes." (PMID 36431071, 2022).
AIDS (2 papers, 2016 to 2022). A syndrome resulting from the acquired deficiency of cellular immunity caused by the human immunodeficiency virus (HIV). "Consequently, the inhibition of HSF1 decreased latency reversal, and thus negatively modulating this factor holds the potential to delay the acquired immunodeficiency syndrome (AIDS)." (PMID 35485710, 2022). "Combined with anti-tumor therapy, the promotion of HSF1 activation might be an appropriate solution to antagonize provirus, resulting in the development of a cure for AIDS." (PMID 27189267, 2016).
atrial fibrillation (2 papers, 2015). A disorder characterized by an electrocardiographic finding of a supraventricular arrhythmia characterized by the replacement of consistent P waves by rapid oscillations or fibrillatory waves that vary in size, shape and timing and are accompanied by an irregular ventricular response. "In Hsf1 Activators Lower cardiomyocyte damage: Towards a novel therapeutic approach to REVERSE atrial fibrillation (HALT & REVERSE), we will focus on the electropathological substrate of AF and dissect the mechanism of protection." (PMID 25947079, 2015).
breast adenocarcinoma (2 papers, 2021 to 2022). "To directly test the hypothesis, we overexpressed HSF1 in the breast adenocarcinoma MCF7 cells." (PMID 33593922, 2021). "To investigate how HSF1 level affects the response to proteotoxic stress, we integrated data from functional genomics analyses performed in MCF7 breast adenocarcinoma cells." (PMID 36010586, 2022).
cholangiocarcinoma (2 papers, 2024). A carcinoma that arises from the intrahepatic biliary tree (intrahepatic cholangiocarcinoma) or from the junction, or adjacent to the junction, of the right and left hepatic ducts (hilar cholangiocarcinoma). "Overall, the present data underline the overexpression of HSF1 in cholangiocarcinoma." (PMID 39243039, 2024). "In cholangiocarcinoma, CAF-secreted TSP-4 binds to integrin α2 on cancer cells, activating HSF1 and Akt signaling pathways." (PMID 39534084, 2024). "Activated HSF1 further enhances TGF-β1 expression and secretion, inducing the transformation of fibroblasts into CAFs and creating a positive feedback loop that promotes cell proliferation and advances cholangiocarcinoma progression." (PMID 39534084, 2024).
colorectal adenocarcinoma (2 papers, 2022 to 2024). The most common type of colorectal carcinoma. "In line with the in vitro data, a diclofenac treatment also radiosensitizes LS174T colorectal adenocarcinomas with a reduced LDH activity and HSF1 expression in a murine xenograft tumor model." (PMID 38229111, 2024). "LDH activity and the expression of HSF1, Hsp70 and Hsp27 decreased in the LS174T and LoVo colorectal adenocarcinoma cell lines with lower basal HSP levels, but not in A549, MDA-MB-231 and COLO357 cells." (PMID 38229111, 2024).
colorectal tumors (2 papers, 2018 to 2021). "In colorectal tumors, DAPK can phosphorylate HSF1, meanwhile, HSF1 can increase the expression of DAPK." (PMID 30546056, 2018).
cystic fibrosis (2 papers, 2014). Autosomal recessive disorder caused by pathogenic variants in the CFTR gene (cystic fibrosis transmembrane conductance regulator), which encodes a chloride and bicarbonate channel expressed in epithelial cells, and follow the diagnosis criteria. "Levels of active trimeric HSF1 and of several of its target chaperones were also increased in the cystic fibrosis cells." (PMID 25405339, 2014).
dementia (2 papers, 2018 to 2022). Loss of intellectual abilities interfering with an individual's social and occupational functions. "Meanwhile, HSF1 agonists can improve cognitive function in dementia models and activation of neuroprotective signaling pathways." (PMID 30096819, 2018). "HSP90AA1, involved in heat shock response (and its master regulator, i.e., HSF1), and EGFR are most important genes in pathology of dementia apart from KRs, given their presence as KRs as well as hubs in RN." (PMID 35327643, 2022).
ependymoma (2 papers, 2022 to 2024). A WHO grade II, slow growing tumor of children and young adults, usually located intraventricularly. "The authors found that high expression of TPR was associated with increased HSF1 and HSPA/HSP70 expression in ependymoma patients and showed that MTOR inhibition by rapamycin therapeutically suppressed TPR expression and reduced tumor size in an ependymoma mouse xenograft model." (PMID 36197606, 2022). "Furthermore, TPR protects cells from RNA-mediated replication stress by regulating heat-shock transcription factor 1 (HSF1) mRNA trafficking, maintaining mTORC1 activity to phosphorylate Unc-51-like kinase 1 (ULK1), and preventing macroautophagy/autophagy induction in ependymoma." (PMID 39080077, 2024).
hepatitis B (2 papers, 2014 to 2021). "Multiple bacterial or vital infection processes, including herpes simplex virus 1 infection, human papillomavirus infection, human immunodeficiency virus 1 infection, hepatitis B, and higellosis, also correlated with HSF1." (PMID 34239690, 2021).
HIV-1 infection (2 papers, 2016 to 2022). The type species of lentivirus and the etiologic agent of acquired immunodeficiency syndrome (AIDS). "In the early stage of HIV-1 infection, HSF1 can promote the replication of HIV-1 and the expression of viral genes." (PMID 35954175, 2022).
idiopathic pulmonary fibrosis (2 papers, 2019 to 2020). Idiopathic pulmonary fibrosis (IPF) is a nonneoplastic pulmonary disease that is characterized by the formation of scar tissue within the lungs in the absence of any known cause. "RT-qPCR and western blot analyses suggested that compared with control mice, mRNA expression of YY1 and HSF1, and expression of miR-214 in the mice with bleomycin-induced pulmonary fibrosis were significantly increased and the expression of THY1 was notably decreased (P < 0.05)." (PMID 32396525, 2020). "HSF1 has been indeed identified as a key regulator of idiopathic pulmonary fibrosis." (PMID 31752429, 2019). "To further verify the implications of the YY1/HSF1/miR-214/THY1 axis in IPF development, we used bleomycin to induce a mouse pulmonary fibrosis model." (PMID 32396525, 2020).